TF (transferrin)
Diseases named in the same sentence as TF in open-access papers (continued):
Sharing a sentence is not in itself a finding about the gene and the disease.
Gaucher disease (2 papers, 2007 to 2012). Gaucher disease (GD) is a lysosomal storage disorder encompassing three main forms (types 1, 2 and 3), a fetal form and a variant with cardiac involvement (Gaucher disease - ophthalmoplegia - cardiovascular calcification or Gaucher-like disease). "While high ferritin with normal serum iron and normal transferrin saturation is expected in Gaucher disease, the possibility of concurrent genetic haemachromatosis should be eliminated." (PMID 17655728, 2007).
glomerular diseases (2 papers, 2012 to 2017). "Increased urinary TF excretion has been suggested to precede the development of microalbuminuria in glomerular diseases." (PMID 28158993, 2017). "Urinary TF results from abnormal permeability of the glomerular basement membrane, and it has been suggested to be a marker for early stages of glomerular diseases." (PMID 28158993, 2017). "Urinary transferrin, which results from abnormal permeability of the glomerular basement membrane, is suggested to be a marker for early stages of glomerular diseases." (PMID 22607047, 2012). "Increased urinary transferrin excretion may precede the development of microalbuminuria in glomerular diseases." (PMID 22607047, 2012). "Over the past decades, urinary protein markers, including urinary IgG, albumin, transferrin, α1-microglobulin, β2-microglobulin and N-acetyl-β-glucosaminidase (NAG), have been widely used in clinic to evaluate renal injury in patients with glomerular diseases." (PMID 22607047, 2012).
gonococcal infection (2 papers, 2022 to 2024). "In terms of the time to infection clearance, mice in the monovalent vaccine group were completely cleared of gonococcal infection on day 9, while for those in the PBS and pCold-TF control groups, clearance was achieved on day 10 (P < 0.01)." (PMID 39660148, 2024).
hemophilia B (2 papers, 2019 to 2024). Hemophilia B is a form of hemophilia characterized by spontaneous or prolonged hemorrhages due to factor IX deficiency. "Thus, this project provides the evidence for the feasibility of using transferrin (Tf) based fusion protein as an approach to develop an oral FIX dosage form for hemophilia B patients." (PMID 31861459, 2019).
hereditary anemia (2 papers, 2020 to 2022). "Our data supports that non-transfusion-dependent hereditary anemia patients have increased dietary iron absorption and decreased iron utilization despite fast uptake of transferrin-bound iron." (PMID 32041196, 2020).
Hodgkin's disease (2 papers, 1973 to 2020). "In Hodgkin's disease abnormal ferritinaemia is associated with a low concentration of transferrin-bound iron and appears to result from a block of reticuloendothelial iron release." (PMID 4511989, 1973). "Likewise, Hodgkin’s lymphoma is also reported to be associated with a low serum iron concentration and reduced transferrin saturation." (PMID 33585190, 2020).
hyperthyroidism (2 papers, 2016 to 2022). Overactivity of the thyroid gland resulting in overproduction of thyroid hormone and increased metabolic rate. "Ferritin was increased, while transferrin and CRP were reduced during hyperthyroidism." (PMID 26866603, 2016).
Hypoglycemia (2 papers, 2008 to 2022). A decreased concentration of glucose in the blood. "Therapy with oral galactose improves hypoglycemia, endocrine abnormalities and coagulation as well as transferrin glycosylation pattern." (PMID 35422763, 2022). "Therapy with mannose (which can be converted to mannose-6-P by hesokinase enzyme) restores intestinal and hepatic function, coagulation, hypoglycemia and the isoelectrofocusing of serum transferrin." (PMID 35422763, 2022).
hypogonadism (2 papers, 2021 to 2023). A disorder characterized by decreased function of the gonads. "The study concluded that abnormal activity of both transferrin and ferritin were associated with hypogonadism and Fe accumulation may lead to reduced sperm production." (PMID 34555113, 2021).
injury (2 papers, 2009 to 2017). Damage inflicted on the body as the direct or indirect result of an external force, with or without disruption of structural continuity. "Transferrin is generated in the liver as the major serum iron-binding protein in the body, and both transferrin and the transferrin receptor were found to change expression during chemically induced liver injury." (PMID 28115551, 2017). "We have previously identified other proteins such as transferrin, clusterin, serum amyloid protein, hemoglobin α-2, and α-2 HS-glycoprotein that were elevated in patients with acute lung injury; however, these proteins were not differentially abundant in this study." (PMID 19432985, 2009).
iron-refractory iron-deficiency anaemia (2 papers, 2012 to 2020). "In human patients and mice with iron-refractory iron deficiency anemia (IRIDA), a genetic impairment of MT-2 was observed to cause microcyter, hypochrom anemia with low transferrin saturation." (PMID 31659405, 2020).
leprosy (2 papers, 2017 to 2018). Leprosy is a chronic infectious disease affecting primarily the skin and peripheral nervous system. "Total iron-binding capacity (TIBC) and transferrin saturation were also lower, while high ferritin levels were twice as common in those with leprosy than in the controls (37% and 16%, respectively)." (PMID 29534113, 2018). "Most leprosy patients with plantar ulcers have normal levels of serum albumin and transferrin and high CRP levels, which indicates the presence of an inflammatory process." (PMID 28866982, 2017). "Nutritional depletion of transferrin was observed in 14.3% of patients with paucibacillary leprosy and 44.3% of patients with multibacillary leprosy (P = 0.0447)." (PMID 28866982, 2017). "Analysis of serum transferrin levels showed that 85.7% of patients with PB leprosy and 55.7% of patients with MB leprosy maintained normal levels." (PMID 28866982, 2017). "Nutritional depletion of transferrin was observed in 14.3% of patients with PB leprosy and 44.3% of patients with MB leprosy." (PMID 28866982, 2017). "In our study, most leprosy patients with plantar ulcers had normal serum levels of albumin and transferrin, but high serum CRP levels, which indicate the existence of an inflammatory process." (PMID 28866982, 2017). "A significant difference in serum transferrin levels was observed between the clinical forms of leprosy (P < 0.05)." (PMID 28866982, 2017).
liver failure (2 papers, 2021 to 2025). A liver disease characterized by the liver losing or has lost all of its function. "Serum transferrin levels represent an independent predictor of mortality in patients with liver failure." (PMID 33593348, 2021). "Thus, transferrin constitutes both a prognostic and a mechanistic biomarker and an attractive surrogate for therapeutic trials aiming to preserve HNF4α signaling as a tool to prevent the development of liver failure." (PMID 33593348, 2021). "Second, lowered transferrin levels may not be only an indicator of imminent liver failure, but also a promising candidate for plasma-based therapeutic interventions." (PMID 33593348, 2021).
lung adenocarcinoma (2 papers, 2017 to 2021). A carcinoma that arises from the lung and is characterized by the presence of malignant glandular epithelial cells. "To determine if motif prediction was representative of actual TF factor binding patterns within enhancers, we reanalyzed publicly available ChIP-seq data that was generated in A549 cells, a cancer cell line derived from lung adenocarcinoma." (PMID 34922464, 2021).
malabsorption syndrome (2 papers, 2021 to 2026). A syndrome resulting from the inadequate absorption of nutrients in the small intestine. "Immunoglobulin and lymphocyte loss frequently accompanies protein loss, such as albumin, lipoprotein, fibrinogen, transferrin, and ceruloplasmin, through the intestinal tract, in patients with malabsorption syndrome." (PMID 37744114, 2021).
medulloblastoma (2 papers, 2013 to 2019). A malignant, invasive embryonal neoplasm arising from the cerebellum. "c-Met activation induced TF expression leads to cell migration in medulloblastoma." (PMID 24086497, 2013).
mesothelioma (2 papers, 2014 to 2023). A usually malignant and aggressive neoplasm of the mesothelium which is often associated with exposure to asbestos. "Only a very weak predisposition to develop mesothelioma was found for the recessive genotype GG when SNP rs2715631 in the Transferrin gene data were statistically compared in these two groups." (PMID 37942251, 2023). "Transferrin was lower in the mesothelioma group than in the other two groups (P < 0.001)." (PMID 24592197, 2014).
metabolic acidosis (2 papers, 2012 to 2022). "The various metabolic derangements predispose HIV patients to metabolic acidosis which promotes reduced binding of iron molecules to transferrin with resultant increase in serum free iron." (PMID 23245266, 2012).
microcephaly (2 papers, 2018 to 2019). A congenital or acquired developmental disorder in which the circumference of the head is smaller than normal for the person's age and sex. "A SOX2-bound neural enhancer within the Akt3 gene is connected to the Zbtb18 (ZFP238 in man) TF gene, whose mutation causes microcephaly in man and mouse; in man, deletions including AKT3, or translocations separating AKT3 from ZFP238 also cause microcephaly." (PMID 30849367, 2019).
monocytic leukemia (2 papers, 2011 to 2023). "The PPAR-γ agonist inhibited TF expression in response to TNF-α in human umbilical vein endothelial cells, human monocytic leukemia cell line, and human umbilical arterial smooth muscle cells." (PMID 22140576, 2011).
mucormycosis (2 papers, 2015 to 2024). "In addition, the accompanying acidosis increases the susceptibility to mucormycosis since the iron required for hyphal growth is released from transferrin as the blood pH drops." (PMID 25664192, 2015).
mucositis (2 papers, 2020 to 2022). Mucositis is inflammation and damage of the mucous membranes lining the mouth and other parts of the gastrointestinal (GI) tract. "The most frequency AEs were polyuria (8/50.0%), fecal occult blood (positive for transferrin) (5/31.3%), creatinine increased (3/18.8%), mucositis oral (3/18.8%) and the proportion of neutrophils decreased (3/18.8%), respectively." (PMID 36408263, 2022). "However, 15 AEs occurred in the placebo group (6/100%), which was similar to WXFL10203614 groups, such as polyuria (4/66.7%), mucositis oral (3/50.0%), fecal occult blood (positive for transferrin) (2/33.3%)." (PMID 36408263, 2022).
myocarditis (2 papers, 2022 to 2023). Myocarditis is a condition that is characterized by inflammation of the heart muscle (myocardium). "Since RUNX3 exhibits higher expression levels across all cell subpopulations than RUNX2, we propose RUNX3 as the primary TF upregulated during acute myocarditis." (PMID 37264110, 2023). "Thus, the TF RUNX3 showed the highest increase in activity during myocarditis." (PMID 37264110, 2023).
nephrosis (2 papers, 2013 to 2025). Pathological processes of the KIDNEY without inflammatory or neoplastic components. "Similarly, a marked increase in the urinary excretion of transferrin and iron has been observed in patients with nephrosis." (PMID 40620843, 2025).
oral squamous cell carcinoma (2 papers, 2023 to 2024). "Furthermore, a saliva proteomic analysis, including oral squamous cell carcinoma (OSCG) patients, identified transferrin as a potential salivary biomarker for the diagnosis of early-stage OSCG." (PMID 37623833, 2023).
periodontal disease (2 papers, 2016 to 2025). "Further studies are necessary with larger sample sizes to determine whether transferrin serum levels can be used as diagnostic markers for periodontal diseases." (PMID 27651883, 2016). "Only a few studies are available on the relationship between transferrin serum levels and periodontal disease." (PMID 27651883, 2016). "Transferrin, which carries iron, is affected in periodontal disease." (PMID 41009972, 2025). "In the present study, the effects of periodontal disease and non-surgical periodontal treatment on transferrin serum levels were evaluated." (PMID 27651883, 2016). "Therefore, the present study was undertaken to evaluate changes in the serum levels of transferrin in patients with periodontal disease and periodontally healthy subjects, before and after non-surgical treatment, and its relationship with clinical periodontal parameters." (PMID 27651883, 2016).
plague (2 papers, 2017 to 2019). Plague is a severe bacterial infection caused by the gram-negative bacterium Yersinia pestis. "An increase in transferrin and hemopexin is highly correlative with anti-microbial activity and protection against plague in mice immediately after attenuated Yersinia pasties vaccine administration, with protection involving biological activities of host iron and heme-binding proteins." (PMID 30778356, 2019).
prediabetes (2 papers, 2023). "One subsequent prospective study among 8003 US adults reported that prediabetes individuals with elevated transferrin saturation had substantially increased mortality risk." (PMID 36904197, 2023).
primary biliary cholangitis (2 papers, 2015 to 2020). Primary biliary cholangitis (PBC) is a chronic and slowly progressive cholestatic liver disease of autoimmune etiology characterized by injury of the intrahepatic bile ducts that may eventually lead to liver failure. "We can state that the serum profile of transferrin isoforms in primary biliary cholangitis is specific and differs in comparison to extrahepatic cholestasis." (PMID 32911601, 2020). "The aim of the current study was to provide evidence that primary biliary cholangitis disrupts the function of hepatocytes, resulting in alterations of protein synthesis and glycosylation in the example of transferrin." (PMID 32911601, 2020). "The study objective was to determine the serum profile of transferrin isoforms in primary biliary cholangitis and compare it to transferrin isoforms profile in extrahepatic cholestasis." (PMID 32911601, 2020). "Our results indicate that serum profile of transferrin isoforms alters primary biliary cholangitis and differs in comparison to transferrin isoforms profile in extrahepatic cholestasis." (PMID 32911601, 2020). "We expect that the changes in the serum profile of transferrin isoforms are likely to be disease-specific and can therefore additionally confirm the toxic effect of bile acid retention on the organelle membranes of hepatocytes in primary biliary cholangitis." (PMID 32911601, 2020).
primary Sjögren’s syndrome (2 papers, 2024 to 2025). "Moreover, studies have shown that plasma exosomes from patients with primary Sjögren’s syndrome—represented by ceruloplasmin (CP) and transferrin (TF)—contain epithelial cell-derived proteins involved in ferroptosis." (PMID 40934008, 2025). "Otherwise, proteins involved in the activation of host immune response, like transferrin, were found in tears of patients with Sjogren syndrome but not in patients with dry eye without Sjogren syndrome or normal volunteers." (PMID 39795983, 2024).
protein deficiency (2 papers, 2020 to 2021). "Total protein, albumin, pre-albumin, transferrin, and lymphocyte count should be used to identify patients with protein deficiency." (PMID 34066564, 2021).
pterygium (2 papers, 2014 to 2024). A wedge-shaped fibrovascular lesion arising from the bulbar conjunctiva and extending to the cornea. "SERPINA1 and transferrin (TF) were down-regulated at both protein and transcript levels in pterygium." (PMID 24825356, 2014).
pulmonary TB (2 papers, 2009 to 2025). "At admission, serum ferritin levels were 95.2 ± 38.7 ng/mL, serum iron was 42.6 ± 15.3 μg/dL, and transferrin saturation was 13.9 ± 5.2% in the pulmonary TB group, significantly lower than in the control group (75.3 ± 28.1 ng/mL, 55.0 ± 14.2 μg/dL, and 17.5 ± 4.7%, respectively; all p < 0.0001)." (PMID 40698207, 2025).
rectal cancer (2 papers, 2007 to 2018). A primary or metastatic malignant neoplasm that affects the rectum. "In addition, the parameters used in our study were selected to monitor the postoperative status of rectal cancer patients; more sensitive and accurate markers reflecting nutritional status, such as the levels of prealbumin, retinol-binding protein, transferrin, and iron could not be measured." (PMID 29983709, 2018).
REM sleep behavior disorder (2 papers, 2021 to 2022). A disorder characterized by episodes of vigorous and often violent motor activity during rem sleep (sleep, rem). "In addition, patients with inidiopathic REM sleep behavior disorder (iRBD) were also had a similar TF gene expression with PD patients." (PMID 33994989, 2021).
sarcoma (2 papers, 2022). A usually aggressive malignant neoplasm of the soft tissue or bone. "Based on the TRANSFAC database, we obtained transcription factors as well as motifs for seven genes, and mined transcription factors that have been confirmed by studies in sarcoma based on the TF cancer database." (PMID 36155774, 2022). "Transferrin (Tf) usually binds to the transferrin receptor (TfR1) to transport iron from the intracellular environment into cells in the form of iron-transferrin complexes, a process that is important in ovarian cancer, sarcoma, and other tumors were significantly up-regulated." (PMID 36185243, 2022).
vitamin B12 deficiency (2 papers, 2017 to 2025). A disease characterized by low serum levels of vitamin B12, either inherited or acquired. "Nutritional abnormalities included ferritin, folate, and vitamin B12 deficiency, and low transferrin saturation (TS) levels." (PMID 40709336, 2025).
acute leukemia (1 paper, 2021). A clonal (malignant) hematopoietic disorder with an acute onset, affecting the bone marrow and the peripheral blood. "The transferrin concentration was significantly decreased after HCT, when compared to patients after standard chemotherapy for acute leukemia (p = 0.011)." (PMID 34204310, 2021).
acute promyelocytic leukemia (1 paper, 2012). An aggressive form of acute myeloid leukemia (AML), characterized by arrest of leukocyte differentiation at the promyelocyte stage, due to a specific chromosomal translocation t(15;17) in myeloid cells. "HL-60 cells have been reported to have an absolute requirement of transferrin and insulin for cell proliferation, and have been widely used as a model system for the study of myeloid differentiation, hematopoiesis, and acute promyelocytic leukemia." (PMID 23194296, 2012).
Airway obstruction (1 paper, 2014). Obstruction of conducting airways of the lung. "In BAL cells, the mRNA expression of transferrin, transferrin receptor and ferritin correlated with airway obstruction." (PMID 24789352, 2014).
albinism (1 paper, 2021). A congenital disorder characterized by partial or complete absence of melanin pigment in the eyes, hair, or skin. "We compared the expression patterns of the differentially expressed TF genes and genes involved in metabolic pathways by Pearson correlation analysis and constructed a correlation network to assess possible co-expression or co-regulation patterns in response to plant albinism." (PMID 34271866, 2021).